FADS2 (fatty acid desaturase 2)
Diseases named in the same sentence as FADS2 in open-access papers (continued):
Sharing a sentence is not in itself a finding about the gene and the disease.
tumor (continued). "In this study, the expression of FADS2 in tumours was analysed using the TCGA public database." (PMID 40682485, 2025). "Additionally, a coordinated regulation between FADS1 and FADS2 was noted in response to the tumor microenvironment." (PMID 40430008, 2025). "The relationship between FADS2 and tumor stages was investigated using GEPIA2." (PMID 36788618, 2023). "Finally, the relationship between FADS2 expression and altered functional states in single-cell levels across different tumor cells was explored by the CancerSEA." (PMID 36788618, 2023). "Furthermore, FADS2 mRNA expression was also significantly increased in most tumor tissues than in paired adjacent normal tissues." (PMID 36788618, 2023). "Finally, the relationship between FADS2 expression and altered functional states in single-cell levels across different tumor cells was explored." (PMID 36788618, 2023). "In cBioPortal, the genetic modification of FADS2 in different tumor types was studied." (PMID 36788618, 2023). "In addition, FADS2 correlated with the majority of tumor-infiltrating immune cells, immunoregulatory genes, and chemokines." (PMID 36788618, 2023). "In addition, the relationship between FADS2 expression and altered functional states in single-cell levels across different tumor cells was explored by the CancerSEA tool." (PMID 36788618, 2023). "Combined with these findings, we speculate that FADS2 plays a tumor immune-suppressive role might be partly by promoting the expression of PD-L1 in tumor cells." (PMID 36788618, 2023). "The relationship between FADS2 expression and different functional states in single-cell levels showed that FADS2 expression had a positive relationship with tumor biological behaviors such as inflammation, cell cycle, proliferation, DNA damage, and DNA repair response in tumors." (PMID 36788618, 2023). "Notably, the upregulation of SCD1/FADS2 was commonly observed in metastatic tumor tissues compared to primary tumor tissues in EOC, indicating their clinical significance." (PMID 35547771, 2022). "We demonstrated that dandelion extract could interfere with glycerophospholipids and unsaturated fatty acids metabolism by inhibiting CHKA/PI3K/AKT/FADS2 axis, ultimately resulting in the blockage of cell membrane formation and tumor cell death." (PMID 36147318, 2022). "Furthermore, lower expression levels of SCD, SQLE, FADS2 and TFRC were significantly associated with increased tumor infiltration of DCs and/or B cells." (PMID 35818395, 2022). "FADS2 is a protein involved in an unknown plasticity of the lipid metabolism of some tumor types, suggesting another metabolism modification leading to chemo-resistant phenotype in TGCTs." (PMID 33473258, 2020). "Additionally, FADS2 is regulated by SREBP in various tumours." (PMID 40682485, 2025). "Hence, the ability of DENSPM to simultaneously suppress FASN, SCD, and FADS2 could be of critical importance for successful tumor treatment." (PMID 39337514, 2024). "However, inhibition and genetic ablation of FADS2 suppress tumor growth." (PMID 36788618, 2023). "Thus, 16:1n-10 biosynthesis through FADS2 constitutes an alternative source of MUFA to support the proliferation of the tumor cells, which may involve, among other actions, increasing membrane fluidity." (PMID 35883589, 2022). "The western blot results of protein extraction after tumor milling also indicated that the expression of GPX4, SLC7A11, and FADS2 proteins was decreased in the UA group." (PMID 40535804, 2025). "FADS2 activation promotes epithelial–mesenchymal transition (EMT) and tumor progression in both patient samples and cell-line models, sustaining EMT plasticity through FADS2-mediated desaturation." (PMID 41465101, 2025). "Previous studies have demonstrated the important role of fatty acid desaturase 2 (FADS2) in governing tumorigenesis and tumor metastasis." (PMID 36788618, 2023).
tumor (continued). "Relative expression of delta-6 desaturase (FADS2) and AMP-activated protein kinase (AMPK) were lower in the Tumor group compared to the Reference group." (PMID 36834959, 2023). "FADS2 was also correlated with TMB, MSI, and chemokines, as well as tumor-infiltrating immune cells." (PMID 36788618, 2023). "Three identified candidate genes, FADS2, KIF20A, and G6PD, were highly expressed in LUAD tissues and their high expression correlated with poor patient prognosis, and tumor stage." (PMID 36225575, 2022). "Hence, only dual inhibition of SCD and FADS2 could result in tumor cell death directly." (PMID 36147318, 2022). "In the tumor, the expression of stearoyl–coenzyme A desaturase (SCD) and fatty acid desaturases 2 (FADS2) was lower than in the peritumoral area." (PMID 32392704, 2020). "In the growing tumor area, FADS1, FADS2, SCD, and SCD5 expression positively correlated when using the B2M gene as reference." (PMID 32392704, 2020). "Fatty acid desaturation, which requires molecular oxygen, is inhibited in hypoxic tumor regions (SCD and FADS2)." (PMID 32103057, 2020). "This was confirmed in additional analyses which also showed significant interactions between SNPs in the FADS2 gene, ALA and tumor proliferation, and serum PSA." (PMID 24027672, 2013). "FADS2 and HILPDA showed significantly elevated levels in tumor cells." (PMID 40977891, 2025). "FADS2, PHKG2, and VDAC2 were significantly related to tumor invasion depth." (PMID 38743344, 2024). "It is known that the product of the FADS2 gene is a keyenzyme in the biosynthesis of polyunsaturated fatty acids,including arachidonic acid, which in turn is a precursor ofprostaglandin E2 (PGE2), which promotes tumor growth andmetastasis." (PMID 37965371, 2023). "FADS2 could suppress ferroptosis by inhibiting the accumulation of lipid peroxides (LPO) and intracellular iron and promote tumor initiation and development." (PMID 37158834, 2023). "Last, to substantiate the role of FADS2 in the human adrenal gland, we analyzed its expression in adrenal nontumorous and tumorous tissue." (PMID 37478183, 2023). "Moreover, a positive correlation between SCD1/FADS2 and SCD1/GPX4 in OvCa tumor tissues was observed by regression analysis in TCGA-OV." (PMID 35547771, 2022). "Therefore, the aim of this study was to analyze the mRNA expression of desaturase genes—SCD, SCD5, FADS1, FADS2, and FADS3—in GBM in three tumor zones: necrotic core, growing tumor area, and peritumoral area." (PMID 32392704, 2020). "In contrast to tumor-enriched lipolysis and fatty acid synthesis enzymes that do not require oxygen, fatty acid metabolic genes that require molecular oxygen are depleted in the tumor region, including fatty acid desaturation (SCD, FADS2) and oxidation (ACSL1)." (PMID 32103057, 2020). "Furthermore, NGS analysis revealed that NF-κB/RELA targets including CCL2, CXCL8, EDN1, IL-1β, IL-6, and SERPINE1 were further reduced and several potential tumor suppressors, such as FABP3, FADS2, FDFT1, SEMA6A, and PCK2, were synergistically induced by the Gefitinib-+IKK16 treatment." (PMID 36358633, 2022). "Moreover, the tumor immune estimation resource and TISCH databases showed a significant positive correlation between the expression of SCD and the abundance of CD8+ T cells and macrophage cell infiltration, while the expression of FADS2 was positively correlated with the abundance of B cells." (PMID 38905386, 2024). "In summary, FADS2 may have a non-negligent role in tumor immunity." (PMID 36788618, 2023). "Furthermore, ferroptosis-related genes with copy number amplification (including FADS2, NQO1, ABCC1, ACSF2, HMOX1, FANCD2 and SQLE) demonstrated higher expression in tumour tissues, and those with copy number deletion (including CRYAB, ACSL3, ZEB1) demonstrated lower expression in tumour tissues." (PMID 35145965, 2022).
infection (8 papers, 2012 to 2025). The state of being infected such as from the introduction of a foreign agent such as serum, vaccine, antigenic substance or organism. "This observed expression of FASN throughout EBV-driven B cell immortalization, combined with the observed cytotoxicity of palmitate upon dual SCD1 and FADS2 loss, led us to hypothesize that SCD1 and FADS2 prevent palmitate-induced lipotoxicity throughout infection." (PMID 40403013, 2025). "We found that dual inhibition of SCD1 and FADS2 led to G1/S-phase cell cycle arrest, confirming their importance in maintaining proliferation both early after infection and in immortalized LCLs." (PMID 40403013, 2025). "We confirmed these findings by Western blot, observing a time-dependent increase in SCD1 and FADS2 expression post-infection, compared with primary uninfected B cells." (PMID 40403013, 2025). "Despite significant B cell donor variation, we observed a modest reduction in B cell growth following single SCD1 or FADS2 inhibition on days 4 and 7 post-infection." (PMID 40403013, 2025). "Since several lipid mediators and inflammatory genes modulated by iFADS2 are involved in adaptive immunity against Mtb, we investigated the effect of a systemic inhibition of FADS2 in a mouse model of aerosol infection with Mtb." (PMID 34951591, 2021). "The inverse regulation of Fads1/Elovl5, compared to Fasn/Fads2, at 6hr post infection with Mtb was surprising since all genes are targets of the LXR and SREBP1 regulators of FA metabolism." (PMID 34951591, 2021). "IFNγ-induced decrease in Fasn and Fads2 expression correlated with reduced Abca1 and Dhcr24 transcript levels after 6 hr of infection, suggesting that IFNγ prevents Mtb-induced stimulation of FA biosynthesis through downregulation of LXR and SREBP1 activity." (PMID 34951591, 2021). "Fads1 and Elovl5 transcript levels were transiently repressed at 6hr post infection with Mtb, while on the opposite those of Fads2 were increased from 6hr until 24hr." (PMID 34951591, 2021). "As the infection progressed, FADS2 as well as SCD mRNAs were both significantly reduced (48 hpi)." (PMID 39863099, 2025). "(A) Activities of PUFA biosynthetic enzymes in resting or IFNγ-primed BMDMs, either left untreated (Ctrl), or infected with Mtb and treated with a FADS2 inhibitor (iFADS2) or vehicle control, as determined by a conversion assay from 6 to 24 hr post infection using the ω6 precursor LA-d11." (PMID 34951591, 2021). "FADS2- and ELOVL4-knockdown cells were infected with a high multiplicity of infection (MOI) and internalized DENV viral RNA (vRNA) was quantified at 4 hpi." (PMID 39863099, 2025). "(B) Intracellular growth of Mtb inside differentiated THP-1 wild-type (WT) or FADS2 knockout (KO) clones, as determined by CFU plating at the indicated days post infection." (PMID 34951591, 2021). "The differential gene expression observed at day 15 post-infection demonstrated a consistent pattern of gene up regulation of PHGDH and PSAT1 and down regulation of APOC1, FADS2, FXYD2, KIAA0125, and MMP12 over a period of time in HIV-1 infected PBMC." (PMID 26821323, 2016). "Given their expression during the early stages of infection, we identified that SCD1 and FADS2 were induced by the EBV master transcriptional regulator EBNA2, which is equally responsible for upregulating other metabolic pathways crucial for EBV-driven B cell outgrowth." (PMID 40403013, 2025). "FADS2 activity was not modulated by Mtb in the conditions of the experiment, suggesting that infection-induced upregulation of Fads2 expression takes more than 24 hr to translate into enhanced enzyme activity." (PMID 34951591, 2021). "When additional LXR target genes were examined, FADS2 mRNA levels were not changed by MHV68 infection, and mRNA levels of SCD2 were decreased in infected macrophages." (PMID 30018108, 2018). "Similarly, increased expression of FADS2 and SCD2 LXR target genes was found both at baseline and following infection of LXR−/− macrophages." (PMID 30018108, 2018).
metabolic disorders (8 papers, 2013 to 2025). "Nonetheless, our results are supported by some observational studies in which a modulation by diet on the association of the FADS1 and FADS2 genes with metabolic disorders like MetS has been reported." (PMID 35773659, 2022). "Genetic variation in genes encoding fatty acid desaturases, such as fatty acid desaturase 1 (FADS1), fatty acid desaturase 2 (FADS2), and SCD1, influences lipid metabolism and susceptibility to metabolic disorders." (PMID 41002979, 2025). "In this study, we identified four key genes, including FADS1, FADS2, GLB1, and PNPLA3, associated with both metabolic disorders and inflammation in MAFLD through bioinformatics methods." (PMID 41007773, 2025).
cardiovascular disease (7 papers, 2012 to 2024). "SNPs in the FADS1 and FADS2 group of genes have been known to be strongly linked to an increased risk of cardiovascular disease." (PMID 39070486, 2024). "Together these findings imply that transcriptional regulation of Fads2 may be important for control of vascular tone and so may have implications for risk of cardiovascular disease." (PMID 22509311, 2012).
neurological diseases (2 papers, 2023 to 2024). "The results from MELODI Presto also identified and prioritized metabolic and neurological diseases as potential intermediates between omega-3 fatty acids or FADS1/FADS2 genes and cognitive function, which provided direction for future mechanistic studies." (PMID 38316767, 2024).
bacterial infection (1 paper, 2014). "The poor metabolic potential of HeLa, mainly concerning FADS2 upstream of COX-2 function, calls into question whether these cells represent a good model to unveil fatty acid or downstream eicosanoid effects in the course of intracellular bacterial infection." (PMID 25549244, 2014).
degenerative disease (1 paper, 2016). "These include novel a-DMRs within the promoter of TAOK2 involved in the MAPK signalling pathway implicated in degenerative disease and within the promoter of an isoform of FADS2 associated with liver omega desaturation." (PMID 27663977, 2016).
intestinal ulcers (1 paper, 2015). "In fact, it has been shown that disruption of one of the genes implicated by the overlapping SNPs, FADS2 (a fatty acid desaturase), results in both altered lipid profiles as well as the development of intestinal ulcers and inflammation in mice." (PMID 26374098, 2015).
FADS2 also shares sentences with these, for which no sentence is quoted: Alzheimer disease (3 papers); Breast tumors (3); heart failure (3); allergic disease (2); aortic stenosis (2); autism spectrum disorder (2); esophageal squamous cell carcinoma (2); Hyperglycemia (2); hyperhomocysteinemia (2); Hyperinsulinemia (2); multiple sclerosis (2); prostate carcinoma (2); triple-negative breast carcinoma (2); acute myeloid leukaemia (1); adrenocortical carcinoma (1); age-related macular degeneration (1); alcohol abuse (1); alcoholism (1); allergic rhinitis (1); Allergy (1); basal cell carcinoma (1); bipolar disorder (1); brain cancer (1); breast invasive carcinoma (1); cardiac hypertrophy (1); celiac disease (1); chronic kidney disease (1); clear cell carcinoma (1); clear cell renal carcinoma (1); cocaine addiction (1).
A further 43 diseases each share a sentence with FADS2 in 1 paper.